DTNA (dystrobrevin alpha)
Description:
May be involved in the formation and stability of synapses as well as being involved in the clustering of nicotinic acetylcholine receptors.
Synonyms: DTN-A; DRP3; D18S892E; DTN; DTN-1; DTN-2; DTN-3; LVNC1; MMCKR2
Tractability: Antibody: its Gene Ontology location is reachable by antibodies, with high confidence; UniProt places it where antibodies can reach, with medium confidence. PROTAC: ubiquitination databases record sites on it; its protein half-life has been measured.
Gene: Protein-coding gene on chromosome 18 (34,493,291 to 34,891,844, forward strand). Ensembl gene ENSG00000134769.
Subcellular location: Cytoplasm; Synapse; Cell membrane
Subcellular location (Human Protein Atlas): Cell Junctions; Intermediate filaments; Nucleoplasm
Pathways (Reactome):
Extracellular matrix organization: Formation of the dystrophin-glycoprotein complex (DGC)
Gene Ontology:
Molecular function: protein binding; zinc ion binding
Biological process: chemical synaptic transmission; neuromuscular synaptic transmission; signal transduction; striated muscle contraction; synaptic signaling
Cellular component: cell junction; protein-containing complex; plasma membrane; synapse; cytoplasm
Genetic constraint (gnomAD): Loss-of-function variants: 42 observed, 103.85 expected, observed/expected ratio (o/e) 0.4, 90% interval 0.31 to 0.52. The upper end of that interval is the gene's LOEUF score, 0.52, which puts it in group 2 of 6, group 1 being the genes least tolerant of losing a copy. Missense variants: 798 observed, 996.64 expected, observed/expected ratio (o/e) 0.8, 90% interval 0.75 to 0.85. Synonymous variants: 349 observed, 366.08 expected, observed/expected ratio (o/e) 0.95, 90% interval 0.87 to 1.04.
Gene-disease validity (ClinGen):
ClinGen rates the evidence that DTNA causes each of these diseases.
dilated cardiomyopathy (autosomal dominant): Limited. Cardiomyopathy which is characterized by dilation and contractile dysfunction of the left and right ventricles.
congenital heart disease (autosomal dominant): Disputed. A heart disease that is present at birth.
Homologues: Orthologues: dog DTNA (97% identical), chimpanzee DTNA (96% identical), macaque DTNA (95% identical), guinea pig DTNA (94% identical), mouse Dtna (92% identical), rat Dtna (92% identical), pig DTNA (90% identical), rabbit DTNA (90% identical), tropical clawed frog dtna (85% identical), zebrafish dtna (64% identical), Drosophila melanogaster Dyb (40% identical), Caenorhabditis elegans dyb-1 (34% identical). Paralogues in human: DTNB (61% identical), PLEC (20% identical), DST (19% identical), MACF1 (19% identical), SYNE1 (18% identical), SPTBN1 (17% identical), SYNE2 (16% identical), SPTBN2 (16% identical), SPTBN4 (16% identical), UTRN (16% identical), FLNA (16% identical), SPTB (15% identical), and 24 more.
Diseases named in the same sentence as DTNA in open-access papers:
DTNA is named in the same sentence as 44 diseases in open-access papers, as found by Europe PMC text mining. Sharing a sentence is not in itself a finding about the gene and the disease. The quoted sentences say what the papers report.
cardiomyopathy (5 papers, 2017 to 2025). A disease of the heart muscle or myocardium proper. "We identified further genes that regulate the development of trabeculation (NKX2-5, TBX20, HAND2, NRG1, NOTCH1 and DTNA) and those with evidence of involvement in cardiomyopathies (CRYAB and RIT1 (ARHGEF2))." (PMID 39567769, 2024). "A few lncRNAs are located in the introns of cardiomyopathy-related genes (e.g., TTN, ACTC1, TPM1, JPH2, ANKRD1, DTNA, TMPO, and FHL2) or physically close to these genes." (PMID 32344918, 2020).
Meniere disease (3 papers, 2016 to 2022). A disease of the inner ear (labyrinth) that is characterized by fluctuating sensorineural hearing loss; tinnitus; episodic vertigo; and aural fullness. "By using whole exome sequencing and combining bioinformatics tools, novel variants in DTNA and FAM136A genes have been identified in familial Meniere’s disease, and this genomic strategy will facilitate the discovery of the genetic basis of familial vestibular disorders." (PMID 27083884, 2016).
bladder cancer (2 papers, 2022 to 2024). "In bladder cancer, overexpressed DTNA functions as an oncogene and, along with four other genes, forms a diagnostic model for detecting recurrence and prognosis." (PMID 38818039, 2024). "DTNA is a scaffold protein that maintains the structural integrity of the heart and skeletal muscle and has been proven to predict the survival prognosis of bladder cancer, hepatocellular carcinoma, gastric adenocarcinoma and esophageal cancer." (PMID 36105107, 2022).
congenital heart disease (2 papers, 2020 to 2021). "Many gene loci have been identified that describe a combination of NCCM and other congenital heart diseases, such as hypoplastic left heart syndrome (Dystrobrevin alpha) or Ebstein anomaly (MYH7)." (PMID 32107565, 2020). "Variants in the alpha-dystrobrevin encoding gene DTNA have been reported in patients with congenital heart disease and left ventricular non-compaction (LVNC)." (PMID 33895855, 2021).
dementia (2 papers, 2018 to 2022). Loss of intellectual abilities interfering with an individual's social and occupational functions. "Expression of α-Dystrobrevin (DTNA), which a paralog of DTNB, has been associated with dementia status and P-tau levels in temporal cortex." (PMID 35246634, 2022). "Evaluation of this microarray data revealed strikingly consistent associations with the Allen Aging, Dementia, and TBI dataset for each of the four genes (AQP4, DTNA, MLC1, FXYD1)." (PMID 30120299, 2018). "Using human transcriptomic data, we demonstrate that expression of perivascular astroglial gene products dystroglycan (DAG1), dystrobrevin (DTNA) and alpha-syntrophin (SNTA1), are associated with dementia status and phosphorylated tau (P-tau) levels in temporal cortex." (PMID 30120299, 2018). "Like the established DAC genes AQP4, DTNA, DAG1 and DMD, expression of several endfoot candidate genes differed between dementia-free and subjects with dementia." (PMID 30120299, 2018).
Left ventricular noncompaction cardiomyopathy (2 papers, 2022 to 2024). Left ventricular non-compaction (LVNC) is characterized by prominent left ventricular trabeculae and deep inter-trabecular recesses. "Previous studies have demonstrated the association between the DTNA gene and left ventricular noncompaction cardiomyopathy." (PMID 35148685, 2022). "The functional analysis of this variation confirmed the causal role of the DTNA-p.N49 S mutation in the pathogenesis of left ventricular noncompaction cardiomyopathy by generating a transgenic mouse model expressing the DtnaN49S mutant specifically in the heart." (PMID 35148685, 2022).
prostate carcinoma (2 papers, 2020 to 2024). A carcinoma that arises from epithelial cells of the prostate gland. "At last, the four genes, DTNA, PRR11, TMEM178B, and CACNA1D, were mainly related to gastric cancer or prostate cancer." (PMID 32964043, 2020). "In addition, the three target genes (DTNA, GJB1, and TRPC4) we searched for are also expected to be used for prostate cancer diagnosis and treatment in the future." (PMID 38818039, 2024).
Barth syndrome (1 paper, 2022). Barth syndrome (BTHS) is an inborn error of phospholipid metabolism characterized by dilated cardiomyopathy (DCM), skeletal myopathy, neutropenia, growth delay and organic aciduria. "In particular, dystrobrevin alpha, encoded by DTNA, is causally involved in Barth syndrome, a severe infantile cardiomyopathy, and Frizzled-4 protein, a receptor for Wnt proteins, encoded by FZD4, is causally involved in familial exudative vitreoretinopathy leading to an avascular peripheral retina." (PMID 35053288, 2022).
Cirrhosis (1 paper, 2023). A chronic disorder of the liver in which liver tissue becomes scarred and is partially replaced by regenerative nodules and fibrotic tissue resulting in loss of liver function. "Indeed, a comparison of our top 25 DEGs with an earlier meta-analysis of NT-NASH of 206 NAFLD patients revealed greater overlap of wound healing or liver fibrosis and cirrhosis-related genes, including dystrobrevin alpha (DTNA) and sulfatase 2 (SULF2)." (PMID 37223041, 2023).
congenital heart malformation (1 paper, 2016). A disease that has its basis in the disruption of heart development. "Our study draws attention to DTNA gene whose deficiency was possibly implicated in the described congenital heart malformation, but further careful functional studies are needed." (PMID 26893613, 2016).
Duchenne muscular dystrophy (1 paper, 2020). Duchenne muscular dystrophy (DMD) is a neuromuscular disease characterized by rapidly progressive muscle weakness and wasting due to degeneration of skeletal, smooth and cardiac muscle. "The DTNA gene encodes α‐dystrobrevin, a member of the dystrophin‐associated glycoprotein complex, which has been associated with movement disorders, such as Duchenne muscular dystrophy." (PMID 33113271, 2020).
dystroglycanopathy (1 paper, 2022). "Due to the enrichment of regulatory variants in FKTN and DTNA, we expanded our search to additional dystroglycanopathy genes (LARGE1, POMT1, POMT2) and identified two regulatory variants of interest in LARGE1 in gene-elusive cases." (PMID 35288587, 2022).
heart failure (1 paper, 2021). Inability of the heart to pump blood at an adequate rate to meet tissue metabolic requirements. "The FHOD3 and DTNA genes are considered candidate genes associated with hypertrophic cardiomyopathy, a heart disease that affects all age groups, being the most common cause of heart failure and sudden death." (PMID 34249494, 2021).
heart malformation (1 paper, 2016). "The findings obtained allow to extend the knowledge of the role of DTNA haploinsufficiency in congenital heart malformation, though further comprehensive functional studies are required." (PMID 26893613, 2016).
multiple system atrophy (1 paper, 2020). Multiple system atrophy (MSA) is a neurodegenerative disorder characterized by autonomic failure (cardiovascular and/or urinary), parkinsonism, cerebellar impairment and corticospinal signs with a median survival of 6-9 years. "Another research group performed circRNA sequencing of the brain samples from multiple system atrophy (MSA) patients and identified five circRNAs, namely IQCK, MAP4K3, EFCAB11, DTNA, and MCTP1, that were overexpressed in the white matter of the cortical tissue." (PMID 33269108, 2020).
muscular dystrophy (1 paper, 2020). Muscular dystrophy (MD) refers to a group of more than 30 genetic diseases characterized by progressive weakness and degeneration of the skeletal muscles that control movement. "DTNA is supposed to play an important role in intracellular signaling, and DTNA deficiency in a mouse model led to moderate muscular dystrophy." (PMID 32927262, 2020).
myocardial hypertrophy (1 paper, 2021). "Also, it has been noted that DTNA, as a putative causative gene involved in left ventricular non-compact cardiomyopathy, can effectively regulate myocardial hypertrophy and microtubule structure." (PMID 34138931, 2021).
myotonic dystrophy (1 paper, 2026). An inherited progressive disorder affecting the muscles. "Alternative splicing of DTNA variable region 2 is dysregulated in the muscles of individuals with myotonic dystrophy." (PMID 40944391, 2026).
tumor (2 papers, 2014 to 2023). "The third gene, DTNA, encodes a protein that belongs to the dystrophin family and plays a role in synapse formation and stability, whereas the protein encoded by the fourth gene, FAM189, potentially binds to a WW domain-containing protein involved in apoptosis and tumor suppression." (PMID 25153832, 2014). "Three genes (DTNA, STC2, and TGFBI) were differentially expressed between HNSCC tumor tissue and normal tissue, and STC2 and TGFBI were significantly up-regulated in tumor tissue, which was consistent with the analysis results." (PMID 37964257, 2023).
cancer (1 paper, 2019). A tumor composed of atypical neoplastic, often pleomorphic cells that invade other tissues. "And we found that one TF, E2F3 was related to ESCA, two genes, DTNA and KCNMA1 were related to STAD, while one TF ESR1 and one gene KIT were associated with both of the two types of cancer." (PMID 31888440, 2019).
DTNA also shares sentences with these, for which no sentence is quoted: alcoholic liver diseases (1 paper); bipolar disorder (1); channelopathy (1); diabetes (1); Ebstein anomaly (1); Emery-Dreifuss muscular dystrophy (1); epilepsy (1); esophageal cancer (1); Familial exudative vitreoretinopathy (1); gastric adenocarcinoma (1); gastric cancer (1); heart disease (1); hepatocellular carcinoma (1); hypertrophic cardiomyopathy (1); hypoplastic left heart syndrome (1); Intellectual disability (1); liver fibrosis (1); movement disorder (1); oligospermia (1); teratospermia (1); type 1 diabetes (1); Type 2 diabetes (1); ventricular septal defect (1); vestibular disorder (1).